RNU1-133P (RNA, U1 small nuclear 133, pseudogene)
Gene: Small nuclear RNA gene on chromosome 2 (200,775,584 to 200,775,750, forward strand). Ensembl gene ENSG00000201737.
Homologues: Orthologues: chimpanzee U1 (98% identical), chimpanzee U1 (92% identical), macaque U1 (87% identical), dog U1 (77% identical), mouse Gm26442 (59% identical). Paralogues in human: RNU1-89P (80% identical), RNU1-1 (80% identical), RNU1-2 (80% identical), RNU1-27P (80% identical), RNU1-28P (80% identical), RNU1-3 (80% identical), RNU1-4 (80% identical), RNVU1-18 (80% identical), RNVU1-29 (80% identical), U1 (80% identical), RNU1-11P (79% identical), RNVU1-28 (79% identical), and 133 more.